SYCP1 (synaptonemal complex protein 1)
Description:
Major component of the transverse filaments of synaptonemal complexes, formed between homologous chromosomes during meiotic prophase. Required for normal assembly of the central element of the synaptonemal complexes. Required for normal centromere pairing during meiosis. Required for normal meiotic chromosome synapsis during oocyte and spermatocyte development and for normal male and female fertility.
Synonyms: SCP-1; CT8; SCP1; HOM-TES-14
Tractability: PROTAC: ubiquitination databases record sites on it.
Gene: Protein-coding gene on chromosome 1 (114,854,863 to 114,995,370, forward strand). Ensembl gene ENSG00000198765.
Subcellular location: Nucleus; Chromosome; Chromosome, centromere
Subcellular location (Human Protein Atlas): Cytosol; Nuclear bodies
Pathways (Reactome):
Reproduction: Meiotic synapsis
Gene Ontology:
Molecular function: double-stranded DNA binding; DNA binding
Biological process: protein homotetramerization; chiasma assembly; homologous chromosome pairing at meiosis; homologous recombination; lateral element assembly; meiotic DNA repair synthesis; reciprocal meiotic recombination; spermatogenesis; synaptonemal complex assembly
Cellular component: central element; chromosome; condensed nuclear chromosome; male germ cell nucleus; nucleus; synaptonemal complex; transverse filament; autosome; chromosome, centromeric region
Genetic constraint (gnomAD): Loss-of-function variants: 12 observed, 47.99 expected, observed/expected ratio (o/e) 0.25, 90% interval 0.16 to 0.41. The upper end of that interval is the gene's LOEUF score, 0.41, which puts it in group 1 of 6, group 1 being the genes least tolerant of losing a copy. Missense variants: 476 observed, 481.4 expected, observed/expected ratio (o/e) 0.99, 90% interval 0.92 to 1.07. Synonymous variants: 175 observed, 164.7 expected, observed/expected ratio (o/e) 1.06, 90% interval 0.94 to 1.2.
Homologues: Orthologues: chimpanzee SYCP1 (99% identical), macaque SYCP1 (97% identical), dog SYCP1 (85% identical), pig SYCP1 (82% identical), rat Sycp1 (75% identical), mouse Sycp1 (74% identical), guinea pig SYCP1 (71% identical), tropical clawed frog sycp1 (35% identical), zebrafish sycp1 (30% identical).
Diseases named in the same sentence as SYCP1 in open-access papers:
SYCP1 is named in the same sentence as 24 diseases in open-access papers, as found by Europe PMC text mining. Sharing a sentence is not in itself a finding about the gene and the disease. The quoted sentences say what the papers report.
infertile (6 papers, 2015 to 2025). "In mice, mutations in Syce2 and Sycp1 lead to infertility due to a prophase I checkpoint that removes defective spermatocytes and oocytes." (PMID 40911633, 2025). "Overexpression of SYCP1 produces a synaptonemal complex-like structure, and targeted mutation of this gene in mice results in failure of synapse formation and infertility, indicating that SYCP1 is the main structural element in the SC." (PMID 27548613, 2016). "The infertility of Cfp1Stra8 mice was attributed to meiotic arrest, in which aberrant formation of lateral and central elements resulting in patchy staining of Sycp1 and Sycp3 was detected in a chromosome-spread assay." (PMID 35918532, 2022). "For example, PIWIL1 (piwi-like RNA-mediated gene silencing 1) plays a central role in spermatogenesis and was found to be differentially methylated in infertile patients, while lack of SYCP1 (synaptonemal complex protein 1) in otherwise healthy mice has been found to yield infertility." (PMID 26221191, 2015).
breast cancer (4 papers, 2013 to 2025). A primary or metastatic malignant neoplasm involving the breast. "Yet another study demonstrated antibody response against Synaptonemal complex protein-1 (SCP-1) and Synovial sarcoma X break point 2 (SSX-2) only in 6% and 1% of breast cancer patients." (PMID 23451156, 2013). "This study hypothesized that epigenetic processes, including DNA methylation, influence the expression of identified CG or testis-specific genes, such as SYCP1, ADAD1, SYCE1, PRSS54, DMRTC2, and TEX101, in breast cancer (BC), normal breast (NB), and chronic myelogenous leukemia (CML) cell lines." (PMID 41411337, 2025).
female infertility (3 papers, 2012 to 2020). Diminished or absent ability of a female to achieve conception. "Deficiency of each known SC protein abrogates synapsis, DSB resolution and crossover formation, resulting in complete male/female infertility for SYCP1 and CE proteins, and a sexual dimorphism of male infertility and female subfertility for LE proteins." (PMID 22870393, 2012). "Although SYCP1 is an essential member of the synaptonemal complex in labeling the axes of the chromosome during meiotic prophase I, no pathogenic variants associated with female infertility have been identified in this gene." (PMID 33095795, 2020). "Although SYCP1 is an essential member of synaptonemal complex in labeling the axes of the chromosome during meiotic prophase I, no pathogenic variants associated with female infertility have been identified in these genes." (PMID 33095795, 2020). "In addition to this SYCE3 proteins are required for stabilization of the N-terminal region of SYCP1 within the central element of the synaptonemal complex and for synaptonemal complex extension; SYCE3 knockout mice exhibit both male and female infertility." (PMID 31671664, 2019).
glioma (2 papers, 2006 to 2016). A benign or malignant brain and spinal cord tumor that arises from glial cells (astrocytes, oligodendrocytes, ependymal cells). "SYCP1 is a well-known meiosis marker that is also known to be a prognostic marker in the early stage of several cancers including breast, gliomas, and ovarian cancers." (PMID 27548613, 2016). "SYCP1 is a well-known meiosis marker known as a prognostic marker of the early stage of several cancers, including breast, gliomas, and ovarian cancers." (PMID 27548613, 2016).
lymphoma (2 papers, 2006 to 2022). A malignant (clonal) proliferation of B- lymphocytes or T- lymphocytes which involves the lymph nodes, bone marrow and/or extranodal sites.
male infertility (2 papers, 2020 to 2024). The inability of the male to effect fertilization of an ovum after a specified period of unprotected intercourse. "Knockout of Sycp1 can lead to meiotic defects and, finally, male infertility in zebrafish and mice." (PMID 39765722, 2024).
ovarian carcinoma (2 papers, 2014 to 2016). A malignant neoplasm originating from the surface ovarian epithelium. "Later serological screening of cDNA expression libraries identified further CT antigens including the meiosis specific synaptonemal complex protein 1 (SCP1) in malignant gliomas, breast, renal cell, and ovarian cancer." (PMID 25138049, 2014).
Ataxia (1 paper, 2022). Ataxia refers to impaired coordination of voluntary muscle movement. "Among the top 10 DMR genes, WDR19 was associated with ataxia, SYCP1 regulated the meiosis progress, FAM173B and CCT5 involved chronic pain." (PMID 36344488, 2022).
clear cell renal cell carcinoma (1 paper, 2018). "And copy-number gain of SYCP1 in human clear cell renal cell carcinoma predicts poor survival." (PMID 30466390, 2018).
intracranial aneurysm (1 paper, 2022). "All genes except SYCP1 were expressed in intracranial aneurysm and control cerebral artery tissue, while FMNL2 and TBC1D2 showed high gene expression in these tissues, further prioritizing these genes." (PMID 35228681, 2022).
leukemia (1 paper, 2025). A malignant (clonal) hematologic disorder, involving hematopoietic stem cells and characterized by the presence of primitive or atypical myeloid or lymphoid cells in the bone marrow and the blood. "Leukemia showed an inverse trend, with SYCP1 and ADAD1 hypermethylated, while PRSS54 was strikingly hypomethylated (~0.08 vs. ~ 0.86 normal)." (PMID 41411337, 2025). "In leukemia versus healthy blood donors, SYCP1, ADAD1, and SYCE1 were hypermethylated (~0.35 vs. ~ 0.17, ~ 0.84 vs. ~ 0.44, and ~0.45 vs. ~ 0.09, respectively), while PRSS54 was markedly hypomethylated (~0.08 vs. ~ 0.86)." (PMID 41411337, 2025). "Functional enrichment identified ADAD1 and SYCP1 as key players in BC and leukemia pathways, respectively." (PMID 41411337, 2025). "The contrasting 5-aza-CdR responses in breast versus leukemia models (SYCP1: 8–10-fold induction vs 0.01-fold suppression; TEX101: 2-fold vs 0.2-fold) underscore how cellular context dictates epigenetic vulnerability." (PMID 41411337, 2025). "We comprehensively analyzed differential methylation, survival analysis (Kaplan-Meier), correlation (Spearman’s), and pathway enrichment analysis (GO/KEGG) of CG genes (SYCP1, ADAD1, SYCE1, PRSS54, DMRTC2, and TEX101) in BC and leukemia." (PMID 41411337, 2025). "In leukemia versus healthy donors, GO enrichment revealed that TEX101, ADAD1, PRSS54, and SYCE1 were the most enriched genes, whereas SYCP1 and DMRTC2 exhibited minimal enrichment." (PMID 41411337, 2025).
medulloblastoma (1 paper, 2016). A malignant, invasive embryonal neoplasm arising from the cerebellum. "One region: 1p13.2 (deletion) was found in both HN30 and HN4, derived from primary lesion stages, and SYCP1 gene involved in carcinogenesis in medulloblastoma." (PMID 27501229, 2016).
metastatic disease (1 paper, 2021). "Aberrations in SYCP1 have been associated with progression toward metastatic disease in castrate-resistant PCa." (PMID 34771455, 2021).
renal carcinoma (1 paper, 2018). A carcinoma arising from the epithelium of the renal parenchyma or the renal pelvis. "From the unique set of genes detected by knnAUC, four genes, APOE, DSC2, SEC63 and SYCP1 were reported to be relevant to renal cancer." (PMID 30466390, 2018).
Renal cyst (1 paper, 2025). A fluid filled sac in the kidney. "Further examination of differentially expressed genes in renal cysts and SC transplants demonstrated significant downregulation of key meiotic proteins, including Sycp3 and Sycp1, as well as defects in DSB-related proteins Rad51 and Spo11, which align with our previous findings." (PMID 40386496, 2025).
cancer (10 papers, 2006 to 2025). A tumor composed of atypical neoplastic, often pleomorphic cells that invade other tissues. "Nonetheless, many genes that have been described as targets of Dnmt3b in the mouse, including MAEL, SYCE1, and SYCP1, are aberrantly expressed in human cancers and are listed as cancer testes genes." (PMID 25198254, 2014). "SYCP1 and SYCE1 maintained modest inverse correlations, whereas PRSS54 and TEX101 showed no significant methylation-expression relationship, highlighting the cancer-specific nature of these epigenetic interactions." (PMID 41411337, 2025). "Brother of the regulator of imprinted sites (BORIS), acrosin binding protein (ACRBP), synaptonemal complex protein 1 (SYCP1), and transmembrane protein 31 (TMEM31) cancer/testis antigens have utilized for in silico peptide vaccine design due to their high expression in various tumors." (PMID 38923980, 2024). "NY-SAR-35 antigen, previously unexplored in bioinformatics, shares characteristics with BORIS, TMEM31, ACRBP, and SYCP1 in terms of its high expression on the cancer cells, notable immunogenicity, and absence of expression on the normal cells." (PMID 38923980, 2024).
tumor (9 papers, 2005 to 2026). "For tumor stage, SYCP1 and ADAD1 showed negligible positive correlations (ρ = 0.02, 0.08, respectively), while SYCE1, PRSS54 and DMRTC2 exhibited slight negative correlations." (PMID 41411337, 2025). "The agreement of these expression patterns across independent cohorts confirms the reliability of these gene signatures in tumor biology, with SYCP1 emerging as the most stable biomarker candidate." (PMID 41411337, 2025). "The consistent hypermethylation of SYCP1 across tumor types suggests it may represent a promising target for epigenetic therapies." (PMID 41411337, 2025). "SomInaClust mutational hotspot analysis could confirm one novel tumor suppressor not yet identified in GCG: SYCP1." (PMID 34771455, 2021). "Several immune-related genes were shared across tumor types, with seven genes (CASP3, F2RL1, CD22, RORC, PLA2G6, SYCP1, MAP3K5) common to all four histologies." (PMID 40621458, 2025). "In this study we demonstrate the expression of several key meiotic prophase genes including MOS, SYCP1, REC8, DMC1, STAG3 and SYCP3 in tumour cells." (PMID 16401344, 2006). "Besides MAGEA1, BAGE, and GAGE1 discovered by T-cell epitope cloning, SEREX very soon displayed more tumour antigens with a cancer/testis restricted expression profile (SSX2, NY-ESO-1, and SYCP-1)." (PMID 15715909, 2005). "In their study, samples from three groups (PA, residual PA, and CXPA) were analyzed to identify protein signatures and their results suggested that seven proteins (APOA1, AP1M1, SYCP1, DCD, HBB, HP, and SLC4A1) could be potential signatures for tumor progression or suppression." (PMID 39155517, 2025).
SYCP1 also shares sentences with these, for which no sentence is quoted: colon cancer (2 papers); cyst (2); melanoma (2); chronic myelogenous leukemia (1); malignant glioma (1); sterility (1); triple-negative breast carcinoma (1).